NME5 (NME/NM23 family member 5)
Description:
Functions as part of axonemal radial spoke complexes, which play an important part in the motility of sperm and cilia (By similarity). In vitro, does not display nucleoside diphosphate kinase (NDPK) activity (Probable). Exhibits a 3'-5'-DNA exonuclease activity that removes single nucleotides from the 3' terminus of single-stranded DNA substrates and digests overhanging mismatched 3' termini from double-stranded DNA substrates, possibly participating in DNA nucleolytic processing. Confers protection from cell death mediated by BAX and alters the cellular levels of several antioxidant enzymes, including GPX5 (By similarity). Might be involved in spermiogenesis by enhancing the ability of late-stage spermatids to eliminate reactive oxygen species (By similarity).
Synonyms: NDK5; RSPH23; nm23-H5; CILD48; NM23H5
Tractability: Small molecule: a structure with a bound ligand is known. Antibody: its Gene Ontology location is reachable by antibodies, with medium confidence; the Human Protein Atlas places it where antibodies can reach.
Gene: Protein-coding gene on chromosome 5 (138,115,169 to 138,139,443, reverse strand). Ensembl gene ENSG00000112981.
Subcellular location: Cell projection, cilium; Cytoplasm, cytoskeleton, flagellum axoneme
Subcellular location (Human Protein Atlas): Cytosol; Plasma membrane; Primary cilium
Gene Ontology:
Molecular function: 3'-5'-DNA exonuclease activity; nucleoside diphosphate kinase activity; protein binding
Biological process: DNA catabolic process; spermatid development; cilium movement; flagellated sperm motility; negative regulation of oxidative stress-induced intrinsic apoptotic signaling pathway; nucleoside metabolic process; spermatogenesis; CTP biosynthetic process; GTP biosynthetic process; spermatid differentiation; UTP biosynthetic process
Cellular component: 9+2 motile cilium; axoneme; cilium; radial spoke; sperm flagellum
Genetic constraint (gnomAD): Loss-of-function variants: 11 observed, 12.31 expected, observed/expected ratio (o/e) 0.89, 90% interval 0.56 to 1.47. The upper end of that interval is the gene's LOEUF score, 1.47, which puts it in group 6 of 6, group 1 being the genes least tolerant of losing a copy. Missense variants: 152 observed, 178.31 expected, observed/expected ratio (o/e) 0.85, 90% interval 0.75 to 0.98. Synonymous variants: 44 observed, 58.67 expected, observed/expected ratio (o/e) 0.75, 90% interval 0.59 to 0.96.
Gene-disease validity (ClinGen):
ClinGen rates the evidence that NME5 causes each of these diseases.
ciliary dyskinesia, primary, 48, without situs inversus (autosomal recessive): Moderate.
Homologues: Orthologues: chimpanzee NME5 (99% identical), macaque NME5 (99% identical), pig NME5 (92% identical), guinea pig NME5 (91% identical), rabbit NME5 (90% identical), dog NME5 (89% identical), rat Nme5 (88% identical), mouse Nme5 (86% identical), tropical clawed frog nme5 (73% identical), zebrafish nme5 (65% identical), Drosophila melanogaster CG15547 (23% identical). Paralogues in human: NME8 (35% identical), NME7 (33% identical), NME6 (28% identical), NME3 (22% identical), NME1 (22% identical), NME2 (22% identical), NME4 (21% identical), NME9 (12% identical).
Diseases named in the same sentence as NME5 in open-access papers:
NME5 is named in the same sentence as 16 diseases in open-access papers, as found by Europe PMC text mining. Sharing a sentence is not in itself a finding about the gene and the disease. The quoted sentences say what the papers report.
breast carcinoma (5 papers, 2011 to 2025). "Increased expression of NME5 has been associated with a prolonged survival in breast cancer and may play a role as a tumour suppressor gene." (PMID 40585280, 2025). "NME5 (non-metastatic cells 5, protein expressed in (nucleoside-diphosphate kinase)) gene is homologous to nm23-H1, a tumor suppressor gene whose expression is often lost in urinary bladder cancer and breast cancer." (PMID 21448288, 2011).
Hydrocephalus (3 papers, 2016 to 2022). Hydrocephalus is an active distension of the ventricular system of the brain resulting from inadequate passage of CSF from its point of production within the cerebral ventricles to its point of absorption into the systemic circulation. "This is quite distinct from the Nme5-/- knockout mice, in which hydrocephalus was the predominant feature." (PMID 31479451, 2019). "The additional Alaskan Malamute case with PCD and hydrocephalus from the United States illustrates the phenotypic similarities between NME5 mutant mice and dogs." (PMID 31479451, 2019). "NME5 is highly expressed in ependymal cells and moderate to marked hydrocephalus along with ciliary dysfunction has been observed in mice homozygous for NME575." (PMID 29333229, 2016). "NME5 was identified as a candidate gene for primary ciliary dyskinesia and hydrocephalus cases." (PMID 36006904, 2022). "Nme5-/- knockout mice exhibit doming of the skull, hydrocephalus and sperm flagellar defects." (PMID 31479451, 2019). "Furthermore, NME5 should be considered as candidate gene for unsolved human PCD and/or hydrocephalus cases." (PMID 31479451, 2019). "Furthermore, the results of this study identify NME5 as a novel candidate gene for unsolved human PCD and/or hydrocephalus cases." (PMID 31479451, 2019).
primary ciliary dyskinesia (3 papers, 2018 to 2022). A rare, genetically heterogeneous, primarily respiratory disorder characterized by chronic upper and lower respiratory tract disease. "A knockout mouse for Nme7 shows situs inversus, and the loss of NME5, -7, or -8 causes primary ciliary dyskinesia." (PMID 30111592, 2018).
adenomyosis (1 paper, 2022). The growth of endometrial tissue inside the muscular wall of the uterine corpus. "In this study, the expression of NME5 was downregulated in the endometrium of women with adenomyosis, which may lead to oxidative stress." (PMID 36685847, 2022). "This study identified STEAP1, TOMM20, GLT8D2, and NME5 as potential biomarkers for adenomyosis." (PMID 36685847, 2022). "The expression levels of STEAP1, GLT8D2, NME5, and TOMM20 were downregulated and showed statistical significance (p < 0.05) in the adenomyosis group compared with those in the control group." (PMID 36685847, 2022). "The microarray dataset analysis revealed that the expression levels of TMEM97, GLT8D2, NME5, STEAP1, and TOMM20 were significantly downregulated in the endometrium of women with adenomyosis compared with those in the control group (p < 0.05)." (PMID 36685847, 2022).
diabetic foot ulcers (1 paper, 2023). "Specifically, monocytes/macrophages increased expression of several apoptosis genes (including BCL2, FGFR3, FGFR1, CTH, CASP3, IL19, NME5, and S100A8/9) in diabetic foot ulcers compared to monocytes/macrophages in non-diabetic wounds." (PMID 38127424, 2023).
fusariosis (1 paper, 2017). "Further, human orthologues of 4 genesenriched in neurons, namely tkr-3 (orthologue GPBAR1), ugt-8(orthologue UGT3A2), R05G6.5.1 (orthologue NME5), and srw-85(orthologue GPR142) might act as potential candidates to unravel the link betweenneuronal stress and fusariosis." (PMID 29152379, 2017).
Situs inversus totalis (1 paper, 2019). "None of the Nme5-/- knockout mice or NME5 mutant dogs had situs inversus totalis indicating that NME5 may be dispensable for the establishment of a correct left/right asymmetry." (PMID 31479451, 2019).
cancer (5 papers, 2010 to 2025). A tumor composed of atypical neoplastic, often pleomorphic cells that invade other tissues. "NME5 functions as a tumor suppressor, with mutations linked to aggressive cancer phenotypes and genomic instability." (PMID 40722386, 2025). "NME5 plays a key role in DNA proofreading and repair and would be predicted to be associated with low-risk cancers." (PMID 34131308, 2021). "NME5 belongs to a family of nucleoside diphosphate kinases (NDKs) that is overexpressed in cancers and was reported to play a major role in promoting cell survival in a mouse model." (PMID 20706582, 2010).
tumor (5 papers, 2012 to 2025). "Additionally, we also found a slight indication that UBE2C and SCUBE2, SERPINA11, and NME5 were associated with tumor differentiation (P = 0.06 and P = 0.09, respectively), inflammatory infiltration (P = 0.09), and p16 expression (P = 0.08), respectively." (PMID 24885002, 2014).
NME5 also shares sentences with these, for which no sentence is quoted: bladder cancer (2 papers); ciliopathies (1); colorectal cancer (1); gastrointestinal stromal tumor (1); invasive breast carcinoma (1); prostate carcinoma (1); situs inversus (1).